TP53INP1 (tumor protein p53 inducible nuclear protein 1)
Diseases named in the same sentence as TP53INP1 in open-access papers (continued):
Sharing a sentence is not in itself a finding about the gene and the disease.
cancer (continued). "Indeed, it has been suggested that cytoplasmic TP53INP1 positively regulates autophagy, which could potentially promote cancer cell survival through the elimination of damaged organelles." (PMID 41345520, 2025). "However, TP53INP1 is often down-regulated in different cancers, including CRC." (PMID 39108882, 2024). "As knocking-out TP53INP1 gene expression promotes, and forced overexpression of TP53INP1 reduces, pancreatic and liver tumorigenesis in mice, the restoration of TP53INP1 expression could be an effective approach for cancer therapy." (PMID 23717325, 2013). "The expression of TF-protein FOXL1 (a regulator of NT5E, TP53INP1, HPGD, FN1, OAS1 and NQO1) is connected with numerous cancer." (PMID 35617355, 2022). "It is crucial to further understand how to control hnRNPA2-mediated TP53INP2 splicing to avoid cancer cell migration, and to retain TP53INP2-mediated autophagy, which synergizes with TP53INP1-induced autophagy." (PMID 23717325, 2013). "While TP53INP2 induces autophagy via mechanisms similar to TP53INP1, an alternative splicing product of TP53INP2 RNA due to hnRNPA2 induces cancer cell migration." (PMID 23717325, 2013). "These miRNAs target the tumour suppressor genes, PTEN, TP53INP1 and TP53INP2, and other proteins involved in cancer development and progression, such as BCL2L2, ERBB4, MAPK9, MCL1, MYCN, VEGFA and VEGFR1." (PMID 20668671, 2010). "Under hypoxic conditions, TP53INP1 suppresses EMT and vasculogenic mimicry, which is the formation of a new tumor vascular supply system, by regulating the ROS/GSK-3β/Snail pathway in breast cancer, which is crucial role in cancer progression and metastasis." (PMID 30671168, 2018). "The observation of the lack of inverse correlation between miR-524-5p and TP53INP1 in some cell lines suggests that, besides regulation by miR-524-5p, other factors are involved in regulating TP53INP1 expression, particularly in cancer cells (see Discussion)." (PMID 28962647, 2017). "Among the DEGs positively modulated in SCE17-exposed cells, we can highlight genes involved in cancer progression, such as FOS, JUN, and JUNB proto-oncogenes, Cyclin Dependent Kinase Inhibitor 1A (CDKN1A), and Tumor Protein 53 Inducible Nuclear Protein 1 (TP53INP1)." (PMID 41440891, 2025). "As such, restoration of TP63INP1 and TP53INP2 expression without the induction of hnRNPA2-mediated TP53INP1 RNA alternative splicing would ideally induce cancer cell cycle arrest, apoptosis, and autophagy, therefore simultaneously inducing binary cell death for a more effective therapy." (PMID 23717325, 2013).
infection (3 papers, 2011 to 2019). The state of being infected such as from the introduction of a foreign agent such as serum, vaccine, antigenic substance or organism. "Even though ATG4D expression was slightly (~2-fold) sustained by 4 hpi and throughout the infection period, TP53INP1 was repressed by 2.6-fold at 8 hpi." (PMID 31969876, 2019). "Using the lentiviral constructs and plasmid infection, the overexpression of TP53INP1 in MDA‐MB‐231 cells and low TP53INP1 expression in transfected MCF‐7 cells were confirmed." (PMID 29655255, 2018).
colorectal (1 paper, 2020). "In a previous study, miR-96 has been substantiated to contribute to colorectal carcinogenesis via targeting TP53INP1, FOXO1 and FOXO3a." (PMID 33183350, 2020).
kidney disease (1 paper, 2024). "Moreover, it was shown that increased whole blood expression of TP53INP1 and L3MBTL3 was associated with an increased risk of kidney disease; TWAS, SMR, and colocalization analysis corroborated this finding." (PMID 39193563, 2024). "Furthermore, it was discovered that elevated whole blood levels of TP53INP1 and L3MBTL3 expression were related to a higher risk of kidney disease; TWAS, SMR, and colocalization analysis all supported this finding." (PMID 39193563, 2024).
TP53INP1 also shares sentences with these, for which no sentence is quoted: esophageal squamous cell carcinoma (2 papers); pancreatic adenocarcinoma (2); pancreatic ductal adenocarcinoma (2); steatosis (2); acute myocardial infarction (1); Beckwith-Wiedemann syndrome (1); brain tumours (1); carcinoma of the bile duct (1); classic Hodgkin lymphoma (1); COVID-19 (1); diabetic nephropathy (1); diabetic retinopathy (1); endometriosis (1); ependymoma (1); gastric MALT lymphoma (1); glial cell tumor (1); glucose metabolism disorder (1); Hepatic steatosis (1); Hyperglycemia (1); Hyperinsulinemia (1); influenza (1); leukemia (1); mycosis fungoides (1); myeloproliferative disorder (1); neurological disease (1); Oral Squamous Cell Carcinoma (1); renal fibrosis (1); skin carcinoma (1); stomach cancer (1); transient neonatal diabetes mellitus (1).
A further 1 disease shares a sentence with TP53INP1 in 1 paper.